SELENON (selenoprotein N)
Diseases named in the same sentence as SELENON in open-access papers:
SELENON is named in the same sentence as 64 diseases in open-access papers, as found by Europe PMC text mining. Sharing a sentence is not in itself a finding about the gene and the disease. The quoted sentences say what the papers report.
congenital myopathy (14 papers, 2007 to 2025). "Human SELENON gene mutations cause SELENON(SEPN1)-related congenital myopathy, characteristically associated with diaphragmatic dysfunction from childhood that is lethal in the absence of ventilator support." (PMID 36830771, 2023). "Selenoprotein N-related myopathy (SEPN1-RM) is a subset of autosomal recessive congenital myopathies due to mutations of Selenoprotein N gene (SELENON or SEPN1)." (PMID 34867752, 2021). "In the congenital myopathy subgroup, 12 of 22 patients (54.5%) had disease-causing variants in RYR1 (n = 4), MYH7 (n = 3), TTN (n = 2), FHL1 (n = 1), NEB (n = 1), and SELENON (n = 1)." (PMID 40494860, 2025). "SELENON (SEPN1)-related myopathy (SELENON-RM) is a rare congenital myopathy characterized by slowly progressive proximal muscle weakness, early onset spine rigidity and respiratory insufficiency." (PMID 34384384, 2021). "Mutations in the selenoprotein N gene (SEPN1) have been identified in individuals with multiminicore disease, muscular dystrophy with rigid spine, and congenital myopathy with fiber-type disproportion." (PMID 33827624, 2021). "Selenoprotein N-related congenital myopathy (SEPN1- or SELENON-RM) is a rare congenital myopathy with an estimated prevalence of 0.5 in 1000,000." (PMID 34384384, 2021). "Mutations in the SEPN1 gene, causing the knockdown of SELENON accompanied by recessive gene RYR1 that encodes ryanodine receptor 1 (RyR1), which are both proteins implicated in calcium homeostasis, cause severe congenital myopathies." (PMID 37958974, 2023).
scoliosis (8 papers, 2007 to 2025). A congenital or acquired spinal deformity characterized by lateral curvature of the spine. "Recessive mutations in SELENON gene encoding selenoprotein N (SEPN1) result in the classic phenotype, with spinal rigidity, respiratory impairment, and early scoliosis as typical characteristics." (PMID 33255644, 2020).
congenital muscular dystrophy (7 papers, 2007 to 2022). A muscular dystrophy that is characterized by diminished muscle tone (hypotonia), progressive muscle weakness and degeneration (atrophy), abnormally fixed joints, spinal rigidity, and delays in reaching motor milestones such as sitting or standing unassisted. "Recently, selenoprotein N (SepN1) polymorphisms have been identified to cause congenital muscular dystrophy." (PMID 28592916, 2017). "Inherited diseases in human selenoprotein genes are rare and only known from case reports describing a form of congenital muscular dystrophy due to mutations in selenoprotein N (SELN)." (PMID 23056383, 2012). "Congenital muscular dystrophy with early rigid spine, also known as the rigid spine with muscular dystrophy type 1 (RSMD1), is caused by SEPN1/SELENON (MIM 606210) mutation." (PMID 35368679, 2022).
muscular dystrophy (7 papers, 2012 to 2024). Muscular dystrophy (MD) refers to a group of more than 30 genetic diseases characterized by progressive weakness and degeneration of the skeletal muscles that control movement. "Of these 30 GOSC genes selected on the basis of involvement in satellite cell biology, only 4 are also included in the 116 myopathogenes, so known to cause muscular dystrophies/myopathies when mutated: these are PAX7, MEGF10, SELENON (formerly SEPN1) and CAPN3." (PMID 34740639, 2022).
respiratory failure (7 papers, 2016 to 2025). The significant impairment of gas exchange within the lungs resulting in hypoxia, hypercarbia, or both, to the extent that organ tissue perfusion is severely compromised. "Selenoprotein N1 (SEPN1) is a protein located in the ER, and its genetic defects can lead to selenoprotein N-associated myopathy (SEPN1-RM), an inherited disorder that causes muscle weakness and respiratory failure." (PMID 41333024, 2025).
Respiratory insufficiency (7 papers, 2007 to 2023). "The pathogenic variants of the SELENON gene, encoding selenoprotein N, have been shown to cause a muscle disease characterized by muscle weakness, spinal rigidity and respiratory insufficiency." (PMID 37375769, 2023). "Gene mutations in SELENON lead to a muscle disorder (SELENON(SEPN1)-Related Myopathy) with muscle weakness predominantly affecting neck and trunk muscles, and life-threatening respiratory insufficiency largely due to diaphragmatic dysfunction." (PMID 36830771, 2023).
rigid spine syndrome (7 papers, 2011 to 2024). "Differentiation from other early-onset conditions involving rigid spine syndrome caused by SELENON, FHL1, LMNA, and others is crucial." (PMID 39468638, 2024). "In the muscular system, genetic maladies involving selenoproteins include multi-minicore diseases (MmD) such as rigid spine syndrome (RSS) resulting from mutations in the human gene encoding Selenoprotein N (SELENON) and an associative dysfunction of the ryanodine receptor 1 (RyR1) receptor." (PMID 30200430, 2018).
muscle disorder (5 papers, 2017 to 2025). "A multifunctional endoplasmic reticulum membrane protein, SELENON has primarily been studied in the context of antioxidant stress defense, calcium homeostasis regulation, and muscular diseases." (PMID 41328592, 2025).
breast carcinoma (3 papers, 2013 to 2022). "Overall, considering both the CCLE and LINCS datasets, eight selenoproteins were overexpressed (DIO2, GPX1, GPX4, SELENOI, SELENON, SELENOS, TXNRD1 and TXNRD3) and five were down-expressed (DIO1, GPX2, GPX3, SELENOP and SELENOW) in TNBC compared to all other “non-TNBC” breast cancer subtypes." (PMID 35158912, 2022).
glioma (2 papers, 2020 to 2025). A benign or malignant brain and spinal cord tumor that arises from glial cells (astrocytes, oligodendrocytes, ependymal cells). "Furthermore, the expression levels of several genes (PLOD3, SLC20A1, ADAM9, FBLIM1, SPOCD1, P4HB, PROS1 and SELENON) were positively correlated with glioma grades." (PMID 32091665, 2020).
selenium deficiency (2 papers, 2020 to 2025). A nutritional deficiency disease resulting from inadequate selenium levels in the body, which can lead to impaired function of selenoproteins essential for antioxidant defense and thyroid hormone metabolism. "Expression of DIO2 and SelenoN in kidneys has also been recognised to upregulate in response to dietary selenium deficiency, with age also playing a factor in upregulation of several others." (PMID 32210049, 2020). "Interestingly, several genes encoding selenoproteins (GPX1, GPX4, SELENON, SELENOM, SELENOF, SELENOW, SELENOT) were also downregulated, suggesting molecular evidence of selenium deficiency." (PMID 40459789, 2025).
SELENON-related myopathies (2 papers, 2019 to 2021). "SELENON-related myopathy (SELENON-RM, formerly SEPN1-RM) is a congenital disorder caused by loss-of-function variants in the SELENON gene." (PMID 34769022, 2021). "SELENON-related myopathies (SELENON-RM) are a group of muscle diseases due to homozygous loss of function mutations in SELENON gene (previously called SEPN1) and characterised by a heterogenous spectrum of clinical features." (PMID 30391828, 2019). "SELENON-related myopathies are a group of congenital disorders arising from loss-of-function mutations in the SELENON gene that affect the muscle system, and lead to life-threatening respiratory malfunction, requiring assisted ventilation, with relative preservation of limb muscles and ambulation." (PMID 30391828, 2019).
Alzheimer disease (1 paper, 2021). A progressive, neurodegenerative disease characterized by loss of function and death of nerve cells in several areas of the brain leading to loss of cognitive function such as memory and language. "Intriguingly, Selenoprotein N deficiency was found to impact ryanodine receptors (RyRs) efficiency by altering its biochemical properties and that intracellular Ca2+ dysregulation in RyRs deficiency has been associated with Alzheimer's disease (AD)." (PMID 34867752, 2021).
Azoospermia (1 paper, 2021). Absence of any measurable level of sperm,whereby spermatozoa cannot be observed even after centrifugation of the semen pellet. "Nevertheless, some causal links between specific selenoprotein deficiencies and phenotypes (e.g., abnormal thyroid function and deiodinase enzymes; low plasma Se and SELENOP, GPX3; azoospermia and SELENOV, GPX4, TXRND3; myopathy and SELENON) can be made." (PMID 34884733, 2021).
COVID-19 (1 paper, 2025). A disease caused by infection with severe acute respiratory syndrome coronavirus 2. "No direct evidence has linked SELENON to viral infection; however, recent studies reported differential SELENON expression in COVID-19 patients, suggesting a potential association with viral pathogenesis." (PMID 41328592, 2025).
dystroglycanopathies (1 paper, 2024). "The most common forms are dystroglycanopathies (DGP; 12–25%), Collagen 6 related disorders (COL6-RD) (12–19%), laminin-alpha 2 related dystrophies (LAMA2-RD; 10–37%), and selenoprotein N related myopathy (SEPN1-RM; 11.65%)." (PMID 38678519, 2024).
lung carcinoma (1 paper, 2021). "SELENOW also has an antioxidant function and overexpression of SELENOW enhance the resistance of hamster ovary and lung cancer cells on H2O2 cytotoxicity SELENON is ubiquitously expressed in muscle, brain, lung and fetal tissue." (PMID 34116728, 2021).
prostate carcinoma (1 paper, 2021). A carcinoma that arises from epithelial cells of the prostate gland. "In prostate carcinoma cells, SeNP did not significantly affect the expression of the seven studied selenoproteins; a twofold increase in the expression of SELENOT, SELENOK, SELENON, and DIO2 can be noted." (PMID 34360564, 2021).
steatosis (1 paper, 2021). Increased lipid within the cytoplasm of cells. "Of these genes, 11 coded for selenoproteins of which four genes had lower expression (SELENON, SELENOO, GPX1, and TXNRD3) and seven genes had higher expression (SELENOK, SELENOS, SELENOW, GPX2, GXP3, DIO1, and SEPHS2) in steatosis." (PMID 34869521, 2021). "Amongst the 13 genes, eight (DIO1, GPX2, SEPHS2, SELENOK, SELENOS, SELENOT, SELENOF, and SELENOW) had higher, and five (DIO3, GPX1, SELENON, SELENOO, and TXNRD3) had lower expression in steatosis." (PMID 34869521, 2021). "Similarly, four out the five genes with lower expression in steatosis also had lower expression in NASH (SELENOO, SELENON, DIO3, and TXNRD3) compared to HC." (PMID 34869521, 2021).
viral infection (1 paper, 2025). "Notably, WNT5A, SELENON, and SLC16A13 exerted similar enhancing effects on both the single-stranded negative-sense RNA virus BPIV-3c and the single-stranded positive-sense RNA virus BEV, highlighting their broad and critical roles in facilitating viral infection." (PMID 41328592, 2025).
myopathy (55 papers, 2009 to 2026). A disease of the muscle in which the muscle fibers do not function properly. "Selenoprotein N (SELENON) is an ER protein whose loss of function leads to human SELENON-related myopathies." (PMID 40507171, 2025). "Oxidative stress and calcium dysregulation occur in SEPN1-related myopathy through selenoprotein N deficiency, reduced sarcomeric reticulum (SR) Ca2+ load, and caffeine-insensitive RyR1 channels." (PMID 40869293, 2025). "Progressive weakness, involving multiple muscle groups (neck, paraspinal, limb), causes axial rigidity, reduced mobility and nocturnal hypoventilation, with this phenotype resembling selenoprotein N-deficient myopathy." (PMID 38042913, 2023). "Many of these neuromuscular diseases are now considered selenoprotein N1 (SELENON also referred to as SEPN1)-related myopathies caused by mutations in the SELENON gene which occurs mainly in humans." (PMID 36532343, 2022). "At that time, only one human disorder was genetically linked to deficiency of a selenoprotein-encoding gene, now known as selenoprotein N (SELENON)-related myopathies, but the situation was soon to change with exome sequencing entering clinical practice." (PMID 33732108, 2021). "Defects in redox homeostasis have also been described in SEPN1-related myopathy, an inherited muscle disease caused by mutations in gene encoding selenoprotein-N (SELENON), which displays clinical and pathological overlap with RYR1-related myopathies." (PMID 34205993, 2021). "Selenoprotein N (SELENON) is an endoplasmic reticulum (ER) protein whose loss of function leads to human SELENON-related myopathies." (PMID 30391828, 2019). "Mutations in the human Selenoprotein N-encoding gene SEPN1 cause various forms of congenital muscular diseases called SEPN1-related myopathies, which are characterized by early-onset hypotonia and weakness." (PMID 24639652, 2014). "N-acetyl-L-cysteine has recently been described as a promising antioxidant in myopathies linked to selenoprotein N or ryanodin receptor defects." (PMID 24098483, 2013). "In fact, NAC pre-treatment has recently been shown to reduce pathological oxidative stress in another myopathies due to selenoprotein N or RYR1 mutations." (PMID 24098483, 2013). "In humans, mutations in the SEPN1 gene, encoding selenoprotein N (SelN), are involved in early onset recessive neuromuscular disorders, referred to as SEPN1-related-myopathies." (PMID 19698141, 2009). "Fatigue and muscle weakness is a recognized feature in several patients and is attributable at least in part to a progressive muscular dystrophy affecting axial and proximal limb muscles, and very similar to the phenotype of myopathy due to selenoprotein N-deficiency." (PMID 34884733, 2021). "However, it has recently shown promise in early-onset myopathies resulting from mutations in the selenoprotein N gene." (PMID 24098483, 2013). "Finally, the patient exhibited myopathy similar to that observed in patients harboring mutations in SEPN1 gene suggesting that R770X mutation perhaps affected the expression of selenoprotein N (SelN)." (PMID 23275319, 2012). "However, only a mutation of selenoprotein N (SelN) leads to a well characterized myopathy." (PMID 29910736, 2018). "In contrast, SELENON/SEPN1 is an ER antioxidant protein, whose mutant variants are found in SEPN1-related myopathy (SEPN1-RM, MIM#602771)." (PMID 39070058, 2024). "Selenoprotein N (SEPN1) is a protein of the endoplasmic reticulum (ER) whose inherited defects originate SEPN1-related myopathy (SEPN1-RM)." (PMID 38402623, 2024). "Using mass spectrometry, we performed a phospholipidomic profiling in the diaphragm of male and female, young and aged, wild type and SelenoN knock-out mice, the murine model of an early-onset inherited myopathy with severe diaphragmatic dysfunction." (PMID 36830771, 2023).
myopathy (continued). "SELENON (SEPN1)-related myopathies share congenital to early onset of muscle hypotonia and weakness in neck, arm, leg and trunk muscles, with severity directly correlating with alterations in body mass index suggesting metabolic impairment." (PMID 34740639, 2022). "SEPN1-related myopathy is an autosomal recessive congenital muscle disease due to inherited defects in Selenoprotein N1 (SEPN1), an ubiquitous ER/SR protein that protects against oxidative stress and is involved in Ca2+ homeostasis." (PMID 36060801, 2022). "Families 5, 6, and 7 all exhibit characteristic phenotypes of SEPN1 myopathies due to defects in SELENON, affected axial muscles, adductors, and sartorius." (PMID 35126314, 2021). "A selective MRI pattern was recognized in selenoprotein N (SEPN1)-related myopathies." (PMID 30804884, 2019). "Core myopathies are caused by mutations in the ryanodine receptor (RYR1), the calcium channel located at the T-tubule/sarcoplasmic reticulum border that is required for excitation-contraction coupling, and by mutations in Selenoprotein-N, a modifier of RYR1." (PMID 19197364, 2009). "Analogical results have been gained in a disease model of selenoprotein N-related myopathy (SELENON-myopathy), a clinical heterogenous muscle disease that shares common features with RYR1-myopathy." (PMID 32823799, 2020).
cancer (5 papers, 2015 to 2025). A tumor composed of atypical neoplastic, often pleomorphic cells that invade other tissues. "In this study, changes in gene expression were observed for SELENOP, SELENOS, and TXNRD3 for all sample groups, while GPX4 was significant in the Irish cancers only and GPX1, SELENOH, and SELENON were differently regulated in the Czech CRCs." (PMID 30469315, 2018). "Thus, GPX1, SELENBP1, SELENON, SELENOK, and SOD2 were differently expressed only in the cancer tissues." (PMID 30469315, 2018). "Notably several of these genes are ER-resident selenoproteins (SELENOF, SELENOM, SELENON, SELENOT), thought to be involved in ER-stress response and calcium flux, comprising a potentially important mechanism of selenoprotein-related cancer prevention or promotion." (PMID 31027226, 2019).
genetic disorder (4 papers, 2011 to 2024). "Nevertheless, the only selenoprotein implicated so far in a human genetic disorder associated with skeletal muscles is selenoprotein N (SelN), encoded by the SEPN1 gene which manifests in muscle dystrophy." (PMID 27822290, 2016). "Selenium is an essential trace element and selenoprotein N (SelN) was the first selenium-containing protein shown to be directly involved in human inherited diseases." (PMID 21858002, 2011).
neuromuscular disease (3 papers, 2011 to 2022). "For example, several neuromuscular disease-causing genes, such as NEBULIN (NEB) and SELENON (SEPN1), overlap these difficult to sequence regions." (PMID 32277129, 2020).
muscular disorders (2 papers, 2011 to 2021). "The causative mutations found in TPM3 and SELENON—genes associated not only with MFM—highlight the phenotypic heterogeneity and clinical overlap between muscular disorders." (PMID 33652732, 2021).
infection (1 paper, 2025). The state of being infected such as from the introduction of a foreign agent such as serum, vaccine, antigenic substance or organism. "We further confirmed that WNT5A, SELENON, and SLC16A13 are key host factors involved in infection by BPIV-3a, as well as by BPIV-3c and other bovine RNA viruses (e.g. BEV)." (PMID 41328592, 2025).
SELENON also shares sentences with these, for which no sentence is quoted: tumor (7 papers); multiminicore disease (5); rectal cancer (4); rigid spine muscular dystrophy 1 (4); Insulin resistance (3); Cachexia (2); centronuclear myopathy (2); colon cancer (2); colorectal (2); nemaline myopathy (2); skeletal muscle disorder (2); adenoma (1); autosomal recessive disease (1); Central core disease (1); Cognitive impairment (1); colorectal adenoma (1); colorectal tumor (1); Duchenne muscular dystrophy (1); dystrophinopathy (1); External ophthalmoplegia (1); Facioscapulohumeral dystrophy (1); glioblastoma (1); inclusion body myositis (1); Kyphosis (1); limb-girdle muscular dystrophy (1); liver cancer (1); malignant glioma (1); metabolic myopathy (1); myotonic dystrophy (1); neuropathy (1).
A further 8 diseases each share a sentence with SELENON in 1 paper.